PASK (PAS domain containing serine/threonine kinase)
Description:
Serine/threonine-protein kinase involved in energy homeostasis and protein translation. Phosphorylates EEF1A1, GYS1, PDX1 and RPS6. Probably plays a role under changing environmental conditions (oxygen, glucose, nutrition), rather than under standard conditions. Acts as a sensor involved in energy homeostasis: regulates glycogen synthase synthesis by mediating phosphorylation of GYS1, leading to GYS1 inactivation. May be involved in glucose-stimulated insulin production in pancreas and regulation of glucagon secretion by glucose in alpha cells; however such data require additional evidences. May play a role in regulation of protein translation by phosphorylating EEF1A1, leading to increase translation efficiency. May also participate in respiratory regulation.
Synonyms: PASKIN; KIAA0135; STK37
Tractability: Small molecule: a structure with a bound ligand is known; a high-quality ligand is known; it has a binding pocket of medium quality; it belongs to a druggable protein family. PROTAC: ubiquitination databases record sites on it; its protein half-life has been measured; a small molecule that binds it is known.
Target class: Protein Kinase; Kinase; CAMK protein kinase group; Enzyme; CAMK protein kinase PASK subfamily; CAMK protein kinase CAMK1 family
Gene: Protein-coding gene on chromosome 2 (241,106,099 to 241,150,852, reverse strand). Ensembl gene ENSG00000115687.
Subcellular location: Cytoplasm; Nucleus
Subcellular location (Human Protein Atlas): Cytosol
Gene Ontology:
Molecular function: phosphatidylinositol binding; protein binding; protein serine/threonine kinase activity; ATP binding; protein kinase activity; protein serine kinase activity
Biological process: negative regulation of glycogen biosynthetic process; protein autophosphorylation; protein phosphorylation; energy homeostasis; intracellular signal transduction; positive regulation of translation; regulation of glucagon secretion; regulation of respiratory gaseous exchange
Cellular component: cytoplasm; cytosol; nucleus
Genetic constraint (gnomAD): Loss-of-function variants: 109 observed, 124.09 expected, observed/expected ratio (o/e) 0.88, 90% interval 0.75 to 1.03. The upper end of that interval is the gene's LOEUF score, 1.03, which puts it in group 4 of 6, group 1 being the genes least tolerant of losing a copy. Missense variants: 1,638 observed, 1,780.3 expected, observed/expected ratio (o/e) 0.92, 90% interval 0.88 to 0.96. Synonymous variants: 685 observed, 750.34 expected, observed/expected ratio (o/e) 0.91, 90% interval 0.86 to 0.97.
Homologues: Orthologues: chimpanzee PASK (98% identical), macaque PASK (94% identical), mouse Pask (72% identical), rat Pask (71% identical), rabbit PASK (70% identical), guinea pig PASK (67% identical), dog PASK (67% identical), pig PASK (64% identical), tropical clawed frog pask (33% identical), zebrafish pask (30% identical), Drosophila melanogaster Pask (23% identical).
Diseases named in the same sentence as PASK in open-access papers:
PASK is named in the same sentence as 26 diseases in open-access papers, as found by Europe PMC text mining. Sharing a sentence is not in itself a finding about the gene and the disease. The quoted sentences say what the papers report.
Obesity (11 papers, 2011 to 2023). Accumulation of substantial excess body fat. "All these effects of PASK deficiency are interesting for states that promote an increase in oxidative stress, such as aging, diabetes, and obesity." (PMID 34943132, 2021). "PASK-deficient mice are protected against the development of obesity, insulin resistance, and hepatic steatosis when they are fed with high-fat diets (HFDs)." (PMID 34444712, 2021). "This led to the study of how PASK deficiency protects against the development of obesity brought on by HFDs, being partly due to a high metabolic rate in skeletal muscle." (PMID 33391184, 2020). "An important finding in PASK’s role in controlling obesity is that its deficiency modifies the physiological response to fasting and refeeding." (PMID 33391184, 2020). "What’s more, PASK deficiency protects against the development of obesity and the insulin resistance induced by HFD." (PMID 31974316, 2020). "PASK-deficient mice are protected against the development of obesity and insulin resistance induced by a high-fat diet (HFD)." (PMID 31974316, 2020). "All these effects of PASK deficiency are interesting for states that promote an increase in oxidative stress, such as aging, diabetes, obesity and others." (PMID 30217996, 2018). "PASK-deficient mice are protected against obesity and the insulin resistance induced by an HFD." (PMID 34943132, 2021). "Additionally, PASK-deficient mice are protected against obesity and the insulin resistance induced by high fat diets." (PMID 30217996, 2018). "While PASK mRNA and proteins are expressed at nearly negligible levels in most tissues under normal conditions, pathophysiological conditions such as high-fat diet and diet-induced obesity modestly but consistently induced PASK expression." (PMID 37443785, 2023). "Accordingly, PASK has also been proposed as a possible target in the treatment of diabetes and obesity." (PMID 34444712, 2021). "PASK is also a hypothalamic nutrient and energy sensor, controlling the development of obesity under an HFD." (PMID 34444712, 2021). "Thus, PASK extensively reprograms metabolism in the liver to drive insulin resistance and has emerged as a potential target for type II diabetes and obesity treatment." (PMID 37443785, 2023). "Interestingly, the functional inactivation of PASK prevents the development of a high-fat diet (HFD)-induced obesity and diabetes." (PMID 34943132, 2021). "PASK has also been proposed as a possible target in the treatment of diabetes and obesity." (PMID 34943132, 2021). "On the other hand, PASK deficiency prevents the development of obesity and non-alcoholic fatty liver in mice fed with a high-fat diet." (PMID 33391184, 2020). "Taken together, this is perhaps another reason why PASK-/- mice fed a high-fat diet could be successfully protected from obesity through the AMPK pathway." (PMID 26371032, 2015). "This was perhaps one of the reasons why PASK-/- mice fed high-fat diet could be successfully protected from obesity, peripheral insulin resistance, and hepatic steatosis." (PMID 26371032, 2015). "Further study of how PASK is regulating the many activities of USF1 may provide additional insight into the role of PAS kinase in human diseases including hyperlipidemia, obesity and diabetes." (PMID 30381292, 2019). "The PASK gene, whereby expression was up regulated in the LBW animals, has been shown to be a metabolic sensor based on mice knock-out studies; mice lacking PASK are resistant to high-fat induced obesity, hepatic steatosis and are resistant to insulin." (PMID 21999700, 2011).
diabetes (7 papers, 2015 to 2021). "For example, diabetes and PASK have been linked, as a human mutation of the PASK gene has been correlated to the maturity-onset diabetes of the young (MODY)." (PMID 33391184, 2020). "Thus, the screen and application of PASK inhibitors that can appropriately regulate GS expression in cells may become a new target of treatment of diabetes and other metabolic diseases." (PMID 26371032, 2015).
Insulin resistance (5 papers, 2015 to 2021). Increased resistance towards insulin, that is, diminished effectiveness of insulin in reducing blood glucose levels. "Aged PASK-deficient mice, therefore, record an overall improvement in their antioxidant mechanism and metabolic phenotype (i.e., PASK deficiency blocks the development of glucose intolerance and insulin resistance in aged mice)." (PMID 34943132, 2021). "Taken together, our results suggest that PASK-deficient mice were protected against developing age-dependent insulin resistance." (PMID 31974316, 2020). "Likewise, insulin resistance (as determined by HOMA-IR) was more than fivefold higher in aged WT compared to aged PASK-deficient mice." (PMID 31974316, 2020). "In any case, PASK inhibits glucagon secretion and decreases the blood glucose level; therefore, it is theoretically possible to treat such metabolic diseases as insulin resistance, inadequate insulin secretion, and type II diabetes by effectively regulating glucagon and insulin secretion." (PMID 26371032, 2015). "In fact, this may be in agreement with the fact that throughout their lives aged PASK-deficient mice maintain the same blood glucose values as young WT mice, and do not develop insulin resistance." (PMID 31974316, 2020). "Previous research has shown that the deletion of PASK (PASK−/−) imparts a protective effect against high-fat diet-induced insulin resistance; however, there have been no reports on the study of insulin resistance of these mice on an HFHS diet." (PMID 34357150, 2021).
Glucose intolerance (4 papers, 2020 to 2021). Glucose intolerance (GI) can be defined as dysglycemia that comprises both prediabetes and diabetes. "The response of aged PASK-deficient mice to a glucose tolerance test (GTT) differed from that of the aged WT, which revealed an apparent glucose intolerance, with blood glucose levels being higher and remaining so for two hours after the glucose injection." (PMID 31974316, 2020). "PASK-deficient mice have better insulin sensitivity and no glucose intolerance, as confirmed by a normal HOMA-IR index." (PMID 31974316, 2020).
neuroblastoma (3 papers, 2018 to 2021). Neuroblastoma (NB) is the most common solid, extracranial childhood tumor. "PASK-deficient mice record an elevated metabolic rate, which has also been confirmed in PASK knockdown myoblast and neuroblastoma cells." (PMID 34943132, 2021). "In previous studies, we have described how PASK plays an important role in GLP-1′s actions in neuroblastoma N2A cells and in the hypothalamic areas involved in feeding behavior." (PMID 34444712, 2021). "PASK is also a critical signaling regulator of AMPK and mTOR pathways in neuroblastoma N2A cells, the hypothalamus, and the liver." (PMID 34943132, 2021). "Previous studies by our group have described PASK as a critical regulator of AMPK and mTOR signaling in hypothalamus, neuroblastoma N2A cells and the liver." (PMID 30217996, 2018).
type 2 diabetes (3 papers, 2015 to 2021). "Some deleterious consequences of type 2 diabetes and HFDs could therefore be reverted by exendin-4 and PASK deficiency and/or inactivation through the regulation of glucose transport and glycogen metabolism, in addition to the lipid metabolism already described." (PMID 34444712, 2021). "Nevertheless, a lower expression of PASK has been reported in pancreatic islets from type 2 diabetic patients." (PMID 30038292, 2018). "Because PASK regulates insulin secretion in β cells, researchers have begun to study the connection between PASK and type II diabetes." (PMID 26371032, 2015).
breast carcinoma (2 papers, 2013 to 2025). "PASK, PSENEN, and RCC2 were shown in breast cancer tissues compared to normal breast tissue, which were upregulated and had a favorable link with cancer progression." (PMID 40725242, 2025). "Other coding SNPs that could include causal variants producing synthetic associations (associations of rare with common SNPs of high penetrance) include SNPs in genes INS-IGF2, ZFYVE26, C16orf46, UNC13A, NRIP1 and CCDC91 for breast cancer and SNPs in SNED1 and PASK for prostate cancer." (PMID 23555315, 2013).
Cirrhosis (1 paper, 2015). A chronic disorder of the liver in which liver tissue becomes scarred and is partially replaced by regenerative nodules and fibrotic tissue resulting in loss of liver function. "Although it is still unknown, it will become a new research area applied in clinical therapy if PASK can down-regulate the expression of inflammation cytokines, inhibiting the deterioration from NAFL to NASH or cirrhosis, which should be addressed in future research." (PMID 26371032, 2015).
COVID-19 (1 paper, 2024). A disease caused by infection with severe acute respiratory syndrome coronavirus 2. "STK39 (serine/threonine kinase 39, DCHT, PASK, SPAK) showed a strong signal in a GWAS meta-analysis of hospitalized COVID-19 patients with severe disease." (PMID 38674024, 2024).
Hypoglycemia (1 paper, 2018). A decreased concentration of glucose in the blood. "Similarly, although the expression of Cpt1a decreased in fasted PASK-deficient mice no hypoglycemia were observed after fasting (24 h or 48 h) in PASK-deficient mice." (PMID 30038292, 2018).
liver diseases (1 paper, 2018). "PASK-targeting could therefore be a good way of reducing the oxidative stress in order to prevent or treat liver diseases." (PMID 30217996, 2018).
multiple sclerosis (1 paper, 2021). A progressive autoimmune disorder affecting the central nervous system resulting in demyelination. "The two-way analysis to identify genes differentially expressed in CSF versus bloodin multiple sclerosis versus non-inflammatory controls yielded four significantgenes: LRRD1, CYP51A1, PASK andYes1." (PMID 34761221, 2021).
nonalcoholic steatohepatitis (1 paper, 2021). "Pharmacologic inhibition of PASK also confirmed its capacity for improving insulin sensitivity, reducing nonalcoholic steatohepatitis caused by an HFD." (PMID 34444712, 2021).
prostate carcinoma (1 paper, 2013). A carcinoma that arises from epithelial cells of the prostate gland. "For prostate cancer the strongest such associations were with SNED1 (412 kb from rs3771570 on chromosome 2, p = 3.5×10−4) and PASK (317 kb from the same index SNP on chromosome 2, p = 4.8×10−4)." (PMID 23555315, 2013).
synucleinopathies (1 paper, 2024). "Beyond known PD genes GBA1 and LRRK2, rare variants AD genes (CD33, CR1 and PSEN2) and Aβ toxicity modifiers involved in RhoA/actin cytoskeleton regulation (ARGHEF1, ARHGEF28, MICAL3, PASK, PKN2, PSEN2) were shared risk factors across synucleinopathies." (PMID 38496508, 2024).
cancer (3 papers, 2020 to 2025). A tumor composed of atypical neoplastic, often pleomorphic cells that invade other tissues. "It was discovered that prognostic risk model-related three genes, including PASK, PSENEN, and RCC2, were upregulated in cancer tissue compared to normal Breast tissue, as shown in." (PMID 40725242, 2025).
metabolic disease (3 papers, 2015 to 2025). A congenital disorder (due to inherited enzyme abnormality) or acquired (due to failure of a metabolically important organ) disorder resulting from an abnormal metabolic process. "Recent studies have shown that PASK is a potential therapeutic target for metabolic diseases as PASK plays a vital role in energy homeostasis, metabolic regulation, and nutrient sensing." (PMID 40725242, 2025). "Further research on the effects and mechanisms of PASK is required to determine its importance as a target for treating metabolic diseases." (PMID 26371032, 2015).
PASK also shares sentences with these, for which no sentence is quoted: dyslipidemia (2 papers); Hepatic steatosis (2); tumor (2); hyperlipidemia (1); lipid metabolic disorders (1); MODY (1); muscle disorders (1); prostate hyperplasia (1); Sepsis (1).